CDH1 (cadherin 1)
Diseases named in the same sentence as CDH1 in open-access papers (continued):
Sharing a sentence is not in itself a finding about the gene and the disease.
tumor (continued). "Such as macrophage migration inhibitor (MIF), polytrophic factor (PTN) and cell adhesion related genes (cadherin, cadherin-1 and desmosomes) are highly expressed in the signaling pattern of tumor cells." (PMID 37213285, 2023). "In many malignancies, CTNNA1 inhibits adhesion, invasion, and induces apoptosis of tumor cells by promoting or collaborating with CDH1 or inhibiting Wnt pathway." (PMID 36741258, 2023). "The most frequently mutated driver genes were RELN, CDH1 and ARID1A, identified in 75%, 65% and 40% of tumor samples, respectively." (PMID 36703611, 2023). "E-cadherin (CDH1) was downregulated at the tumor stage, in accordance with the observed decrease in the attractor patterns and the subsequent loss of tight junctions." (PMID 37270586, 2023). "Some tumors have been observed to regulate the expression of CDH1 during the metastatic process, raising questions about the role of the tumor microenvironment in promoting or inhibiting tumor cell migration and invasion." (PMID 37174083, 2023). "For patients with metastatic ILC, mutations in CDH1, NF1, PIK3CA, and TBX3, measured as tumor mutational burden (TMB), are higher than for patients with metastatic IDC." (PMID 37428725, 2023). "It is interesting to note that CDH1 mRNA and/or E-Cad were upregulated in most cancers in the early stages of tumor development and the levels remained elevated as tumors progressed to later stages across most carcinoma types." (PMID 37189027, 2023). "These cumulative findings indicated that targeting ROS1 with either crizotinib or entrectinib, in conjunction with IN10018-mediated FAK inhibition, enhanced the in vivo anti-tumor effects of either monotherapy in both CDX and PDX CDH1-deficient mouse models." (PMID 37324948, 2023). "The sensitivity of the mutation status of cfDNA to predict mutation in tumor samples was highest in FAT4 (88.9%), followed by MACF1 (80%), CDH1 (75%) and PLB1 (75%)." (PMID 36779847, 2023). "CDH1 has been shown to localize to the surface of tumor EVs and to heterodimerize with vascular endothelial-cadherin on the surface of endothelial cells to promote signaling." (PMID 36470535, 2023). "During epithelial–mesenchymal transition (EMT) in cancer progression, tumor cells switch cadherin profile from E‐cadherin to cadherin‐11 (CDH11), which is accompanied by increased invasiveness and metastatic activity." (PMID 37558205, 2023). "CDH1 (E-cadherin) is a transmembrane protein mediating calcium-dependent cell‒cell adhesion, which can inhibit tumour cell invasion and limit cell motility." (PMID 37885030, 2023). "In summary, the decrease or loss of CDH1 (E-cadherin gene), SMAD4, PTEN, and FAT1 expression leads to an aggressive tumor with an increased invasive phenotype and increased metastatic potential." (PMID 37687058, 2023). "To address this question, we deleted the eQTL in a tumour cell line expressing wild-type E- and P-cadherins, preventing it from interacting with the CDH1 promoter." (PMID 37372088, 2023). "Co-treatment with IN10018 and ROS1 inhibitors significantly reduced the tumor size in CDX models and PDX models with CDH1 deficiency." (PMID 37324948, 2023). "WT1 levels were found to be higher in cancer cells relative to adjacent, non-tumor tissue, while CDH1 levels were lower in the cancer cells as compared to the cancer-adjacent tissue." (PMID 36864480, 2023). "CDH1 upregulation can maintain the stemness characteristics of tumor cells and promote oncogenesis and progression." (PMID 35784532, 2022). "Consistent with a TSK-fibrovascular niche, prominent TSK signaling to FB and Endo was mediated by several common ligand–receptor pairs, including VEGFA-NPR1, VEGFB-NPR1, PGF-SDC1, and CDH1-ITGAE, associated with tumor angiogenesis." (PMID 35908020, 2022). "Statistically significant, slight changes in the expression of the CDH1 gene (Cadherin 1, type 1, E-cadherin epithelial) were observed in fibroblast cells after treatment with tumor-derived exosomes." (PMID 36012171, 2022).
tumor (continued). "In this context, IIH-FH tumours presented reduced CDH1 expression, suggesting an involvement of the EMT in determining this phenotype." (PMID 36253523, 2022). "Mechanistically, it transcriptionally represses CDH1, which leads to loss of E-cadherin expression, EMT induction, and tumor cell invasion." (PMID 35898399, 2022). "Downregulation of Cdh1 has been reported in different tumour types, such as prostate, liver, ovary, brain and breast cancers." (PMID 36499653, 2022). "The APC/C-co-activator Cdh1 is considered a potential tumor suppressor and it is downregulated in different tumor entities." (PMID 35832196, 2022). "It binds to the E‐boxes in the CDH1 promoter and represses transcription of the CDH1 gene encoding an E‐cadherin, thereby boosting the EMT and acquisition of metastatic potential by tumor cells." (PMID 34826187, 2022). "To investigate the correlation between mRNA and protein expression, we examined the differences in CDH1 protein expression between tumor and normal tissues by using Human Protein Atlas Analysis (HPA) database." (PMID 35784532, 2022). "Researchers have observed that 86.1% of BC cases have shown high SALL4 expression, and it is regulating different tumor suppressor genes, including E-cadherin (CDH1) and PTEN." (PMID 36362083, 2022). "Mutations in CDH1 gene have been associated with the development of signet ring cell carcinoma in situ (SRCC-pTis), characterized by tumor cells located between normal foveolar epithelial cells and the basement membrane." (PMID 36556253, 2022). "E-cadherin, which is encoded by CDH1, is involved in EMT and is linked to tumor invasion and diffusion." (PMID 35910224, 2022). "In this study, we demonstrated that Cdh1 is highly expressed in tumor tissues and negatively correlated with overall survival in the TNBC groups." (PMID 35627188, 2022). "The HPA database indicated that the protein expression of CDH1 in BC tumor tissues was significantly higher than that in normal tissues." (PMID 35784532, 2022). "Heterozygous mice lacking Cdh1 showed an increased probability of developing spontaneous tumours, further supporting a role for Cdh1 as a tumour suppressor." (PMID 36499653, 2022). "Our results showed that IIH-FH tumours presented reduced expression of CDH1 and higher expression of TGF-β, suggesting a mesenchymal phenotype." (PMID 36253523, 2022). "Co-treatment with miR34a and doxorubicin slowed tumor growth in MCF-7/A cells via the Snail/CDH1 pathway in vivo." (PMID 35464064, 2022).
tumor (continued). "As the gene with the highest degree in the PPI network, CDH1 was significantly overexpressed in multiple tumor tissues, especially in tumors originating from urogenital tracts, breast, lung, cholangio, cervix, and endometrium, based on TCGA database." (PMID 36131343, 2022). "LAMC2 was upregulated in metastasis epithelial cells, while CDH1 (E-cadherin) was faded in metastasis p-EMT tumor cells." (PMID 35742914, 2022). "APC/C (Cdh1) has a tumor suppressor function in melanocytes mediated by the subunit Cdh1, which inactivates PAX3 through ubiquitination and degradation, implying consequent inhibition of MITF production." (PMID 36274944, 2022). "In this study, we show that Cdh1 is highly expressed in tumor tissues and negatively correlated with the overall survival in the TNBC group." (PMID 35627188, 2022). "Cancer cells in solid areas discard tumor-suppressive adhesion interactions such as CDH1, CADM1, and ESAM with normal epithelial cells in comparison with those in the GG areas." (PMID 35874770, 2022). "The APC/C either has an oncogenic function after binding to its co-activator Cdc20, or works as a tumor suppressor when bound to Cdh1." (PMID 35832196, 2022). "Further investigation revealed that high TME-score was also related with high expression of immunosuppressive molecules, decreased tumor mutation burden (TMB), and high rate of mutation in significantly mutated genes (SMGs) (e.g., PIK3CA and CDH1)." (PMID 35401704, 2022). "Cadherin-1 forms adherence junctions between epithelial cells, suppressing tumour invasion and metastasis." (PMID 36291085, 2022). "The mRNA levels of the CDH1 gene decreased at each stage (I–IV) in the tumor tissues and increased at each stage (I–IV) in the blood." (PMID 36161592, 2022). "ZEB1 binding to the CDH1 promoter caused the recruitment of the CtBP to ZEB1’s CID, which ultimately suppresses CDH1 transcription and promotes tumor progression and metastasis." (PMID 35454770, 2022). "The authors claimed to have found “CDH1 methylation” in 80 primary tumor samples (53%) and 26 sentinel lymph node metastases (90%)." (PMID 36139537, 2022). "ZEB1 is known to play pleiotropic roles in cancer, including promoting EMT by repression of CDH1 to make tumor cells mobile and invasive, and by enhancing cell proliferation by repression of cyclin-dependent kinase (CDK) inhibitor genes such as P15 and P21." (PMID 35404029, 2022). "Overexpression of E-cad on tumor cells infected by engineered HSV expressing CDH1 prolonged the survival in GBM-bearing mouse models." (PMID 35954362, 2022). "Bioluminescence one day after intraductal engraftment was 2-fold higher in glands engrafted with MCF-7:CDH1 cells compared to controls, suggesting that E-cad favors tumor cell survival and/or engraftment in the mouse milk ducts." (PMID 36008376, 2022). "As a consequence, a high burden of tumour invasion and metastasis is related to a deletion in the CDH1 gene, which codes for ECAD." (PMID 36359286, 2022). "Tumour cells isolated from one of these transgenic models (Wcre;Cdh1;F/FTrp53F/F) developed metastatic spread upon orthotopic transplantation of isolated tumour cells, however, it was reported that most tumour cells were ER−." (PMID 35318435, 2022). "On the other hand, in domain 4, we observed upregulation of KRT8, AQP3, KLHDC7B and CDH1, which tend to exhibit stronger tumor progression and metastasis, and high expression of genes NUPR1 and DBI associated with chemotherapy resistance." (PMID 36250636, 2022). "As shown, the CDH1 reconstitution in CRC cells with AFF4 depletion led to a deficiency of cell migration and invasion; hence, we confirmed that AFF4 served as a tumor suppressor in CRC metastasis via upregulating CDH1." (PMID 35223479, 2022).
tumor (continued). "IHC of formalin fixed paraffin embedded (FFPE) tumors showed increased expression of CDH1 on tumor cell membranes after miR-200c restoration." (PMID 34045467, 2021). "In the context of HDGC, synthetic lethal partner genes of CDH1 can become actionable drug targets, thus resulting in preferential death of the CDH1-null tumor cells." (PMID 35008266, 2021). "For further statistical analysis, quantitative indicators of CDH1 expression in the primary tumor and metastasis were approximated into qualitative ones by dividing the expression level into high and low median 140 and 220, respectively." (PMID 34237057, 2021). "Proteins related to cell proliferation, growth, and apoptosis like BCL-X, HIF-1α, HNF-3β, and HO-1/HMOX1 were also downregulated, that is, related to tumor progression, whereas upregulation of E-cadherin (CDH1) was observed after chrysin treatment." (PMID 35096000, 2021). "miR-101 has been reported to act as a tumor suppressor by targeting CDH1 inhibitors, such as ZEB1/ZEB2 and EZH2 in different tumors." (PMID 34943943, 2021). "IL-6 aids in EMT via JAK-STAT3 or NF-κB pathways by activating EMT-TFs such as Snail, Slug, Twist, and Zeb1 which in turn reduces expression of CDH1 that drives migration and invasion of the tumor." (PMID 34220337, 2021). "Results from gastric normal vs. tumor tissues revealed CDH1 downregulation in six IGC tissues (06/07, 09/07, 12/08, 05/09, 17/11 and 18/11) and CDH1 upregulation in two IGC tissues (08/07 and 10/12)." (PMID 34066170, 2021). "CDH1 (or E-cadherin), a member of the cadherin superfamily, is a calcium-dependent cell adhesion protein that functions as a tumor suppressor." (PMID 34926573, 2021). "We tested this possibility further by staining tumor sections with antibodies to E-cadherin (Cdh1), Vimentin (Vim) and pan-Cytokeratins (pan-Ck) to assess EMT as a function of host platelet miRNAs." (PMID 34936674, 2021). "E-cadherin (CdH1), as a tumor suppressor of EMT, has a significant correlation with malignant phenotype, invasion and migration of tumor cells." (PMID 34930256, 2021). "SNAI1, a zinc-finger containing transcription factor, induces EMT by direct suppression of E-cadherin (CDH1) transcription during development or tumor progression." (PMID 34335956, 2021). "The CDH1 gene generates epithelial cadherin or E-cadherin, which helps to inhibit tumor cell invasion." (PMID 35069196, 2021). "On the other hand, the methylation status of CDH1 enhancers showed slight differences between normal and tumor tissues, with an increased methylation especially in the CpG sites of enhancers A, B and E in almost all the cases." (PMID 34066170, 2021). "Results obtained from the analysis of eight IGCs expressing different levels of CDH1 gene showed the presence of some differences in the methylation of CDH1 promoter/enhancers between normal and tumor tissues." (PMID 34066170, 2021). "Considered a tumor suppressor, EZH2 plays a role in silencing CDH1, FOXC1, DAB2IP, and TIMP3, events linked to metastatic progression." (PMID 34680307, 2021). "For example, well-known tumor suppressors or tumor-related genes (CDH1, CDKN2A, DAPK, etc.)are silenced by promoter methylation in CC." (PMID 34745985, 2021). "CDH1 (E-cadherin) expressions always served as tumor suppressors during carcinoma EMT, while the hallmarks of EMT are the upregulation of CDH2 (N-cadherin) and vimentin." (PMID 34631545, 2021).
tumor (continued). "Mechanistically, ID3 exhibits tumor suppressor functions in PTC cells by interacting with E47 to form heterodimers that prevent E47 binding to CDH1 promoter and maintaining CDH1 transcription and epithelial phenotype in PTC cells." (PMID 34462424, 2021). "Although a relationship between sensitivity to EGFR TKIs and tumor E-cadherin expression has been proposed, depletion of cadherin 1 (CDH1) by itself in EGFR-mutant therapy-naïve NSCLC cells does not lead to a loss of EGFR TKI efficacy." (PMID 34572868, 2021). "Like CDH1, CTNNA1 is involved in intercellular adhesion and is a suspected tumor suppressor and susceptibility gene for DGC." (PMID 33868605, 2021). "EPHA2 modulates tumor invasion and metastasis by negatively regulating CDH1 (E-cadherin), while also having a positive correlation with vimentin and β-catenin expression." (PMID 34455105, 2021). "Both epithelial- and mesenchymal-associated genes were commonly expressed at higher levels in CTCs compared to the bulk primary tumour, although some common EMT-associated genes (CDH1, VIM, EGFR, EPCAM) remained unchanged." (PMID 34206049, 2021). "The exogenous signal that promote tumor growth can inhibit the expression of E-cadherin and mediate EMT by forming complex with transcription factors such as Snail, Slug, ZEB1, SIP1 and Twist and binding to the promoter of the CDH1 gene." (PMID 33992097, 2021). "CDH1 serves as a critical tumor suppressor that tethers β-catenin, one of the key molecules for Wnt/β-catenin signaling, around the cytomembrane to suppress its nuclear translocation and transcriptional activation." (PMID 35115926, 2021). "Since then, various studies have proposed the CDH1/E-cadherin coding gene as a tumor suppressor gene by enabling complex mechanisms to promote tissue organization and apoptosis blockade." (PMID 34680444, 2021). "Another gene frequently lost during tumor progression in multiple cancer types is CDH1, which encodes the protein E-cadherin that maintains cell-cell contacts." (PMID 33917049, 2021). "Because CDH1 is a tumor suppressor gene, usually a second somatic hit is required for tumor initiation, which typically involves promoter methylation." (PMID 34073553, 2021). "CDH1 mutations are pathognomonic for ILC and occur in the majority of tumours; loss of E-cadherin has been shown to unequivocally drive the ILC phenotype." (PMID 33919581, 2021). "Tumor cells lose intercellular junction proteins such as E-Cadherin (CDH1) and are able to travel through the extracellular matrix, in a process known as cell migration." (PMID 32707933, 2020). "CDH1, a cellular adhesive protein, plays a role in epithelial-mesenchymal transition (EMT) and is associated with tumor invasion and spread." (PMID 32714095, 2020). "In contrast, PAH was significantly downregulated in tumor tissues than in normal tissues showing a possible regulatory link between the expression levels of Cdh1 and PAH." (PMID 33260674, 2020). "In accordance with the in vitro data the expression of the epithelial marker CDH1 was strongly reduced in the L1low derived tumours compared with the L1high tumours." (PMID 32291413, 2020). "E-cadherin, a cell-cell adhesion molecule, on its downregulation is responsible for tumor growth and a close link between this CDH1 gene and HDGC is studied here." (PMID 33062523, 2020). "CDH1, a classical type I cadherin, has been identified as a BC tumor suppressor and when downregulated it facilitates a more aggressive cancer progression." (PMID 33168853, 2020). "The normal phenotype is restored when malignant epithelial tumor cells are transfected with wild-type CDH1." (PMID 33297397, 2020). "This switch in CDH1 expression was also evidenced in advanced stage CRC, and was linked to tumor dissemination in the abdominal cavity in PMP." (PMID 33266161, 2020). "Inactivation of CDH1 during GC development occurs in the tumour because of genetic and epigenetic changes." (PMID 31949278, 2020).